NPY (neuropeptide Y)
Diseases named in the same sentence as NPY in open-access papers (continued):
Sharing a sentence is not in itself a finding about the gene and the disease.
adrenal tumors (1 paper, 2023). "The increased NPY gene expression in adrenal tumors favored NPY release from the neoplasm, increasing the plasma NPY level." (PMID 37373115, 2023).
airway hyperresponsiveness (1 paper, 2018). "The increase in NPY nerve fibers was associated with airway hyperresponsiveness, suggesting a potential pathological role for NPY." (PMID 30081920, 2018).
Alcohol withdrawal syndrome (1 paper, 2021). "Although the current meta-analysis's findings do not match physiological predictions, decreased expression of NPY has been observed in the alcohol-dependent individuals and during Alcohol withdrawal syndrome (AWS)." (PMID 34777047, 2021).
allergic reaction (1 paper, 2011). "The role of NPY in allergic reaction is still largely debated." (PMID 21245958, 2011).
alopecia (1 paper, 2025). Hair loss usually from the scalp. "Interestingly, these beneficial effects extend beyond body weight, as hypothalamic NPY also appears to mitigate other aging-related features, such as alopecia, which has been previously linked to aging and metabolic alterations." (PMID 40011349, 2025).
amyotrophic lateral sclerosis (1 paper, 2021). Amyotrophic lateral sclerosis (ALS) is a neurodegenerative disease characterized by progressive muscular paralysis reflecting degeneration of motor neurons in the primary motor cortex, corticospinal tracts, brainstem and spinal cord. "However, NPY may be implicated in the disease pathogenesis of amyotrophic lateral sclerosis, and elevated NPY levels in the blood of patients correlated with a shorter disease duration." (PMID 34298907, 2021).
Aqueductal stenosis (1 paper, 2011). Stenosis of the cerebral aqueduct (also known as the mesencephalic duct, aqueductus mesencephali, or aqueduct of Sylvius), which connects the third cerebral ventricle in the diencephalon to the fourth ventricle, which is between the pons and cerebellum. "The same findings were reported for other proteins (neurofilament light protein, tau, sulfatide, vasoactive intestinal peptide and neuropeptide Y) in case of iNPH and aqueductal stenosis." (PMID 21569454, 2011).
artery disease (1 paper, 2023). "It has been reported that in artery neointima NPY and Y1 receptor were localized to macrophages, which indicated NPY may regulate the function of macrophages in artery disease." (PMID 37149580, 2023). "Therefore, the physiopathological role of NPY in arterial disease, especially after vascular injury, remains controversial." (PMID 37149580, 2023).
astrocytomas (1 paper, 2023). "Analogously, NPY-positive neurons in astrocytomas may serve as an additional source of different neuropeptides for neoplastic cells." (PMID 36583743, 2023).
Atrophy (1 paper, 2013). Any weakening or degeneration, especially through lack of use. "We used immunolabeling to detect PARV+ interneurons in fixed sections, and corrected for disease-related striatal atrophy by expressing PARV+ interneuron counts in ratio to interneurons co-containing somatostatin and neuropeptide Y (whose numbers are unaffected in HD)." (PMID 24014043, 2013).
attention deficit-hyperactivity disorder (1 paper, 2017). A disorder characterized by a marked pattern of inattention and/or hyperactivity-impulsivity that is inconsistent with developmental level and clearly interferes with functioning in at least two settings (e.g. at home and at school). "In addition to a gain of the NPY gene in a familial case with EOO and attention deficit hyperactivity disorder, likely pathogenic CNVs included gains of glutamate receptors (GRIK1, GRM7) and the X-linked gastrin-peptide receptor (GRPR), all inherited from obese parents." (PMID 28489853, 2017).
autonomic dysfunction (1 paper, 2025). "Immunofluorescence staining revealed that autonomic dysfunction in AR mice was ameliorated by IL-4 NAb, as evidenced by the up-regulation of TH and NPY and down-regulation of ChAT and VIP in the nose." (PMID 41019284, 2025). "Immunofluorescence staining revealed that autonomic dysfunction in AR mice was ameliorated by minocycline, as evidenced by the up-regulation of TH and NPY and down-regulation of ChAT and VIP in the nasal mucosa." (PMID 41019284, 2025).
bacterial pneumonia (1 paper, 2024). Acute infection of the lung parenchyma caused by bacteria (e.g., Streptococcus pneumoniae, Haemophilus influenzae, Chlamydia pneumoniae, Mycoplasma pneumoniae, and Legionella pneumophila). "The increase in NPY levels may also be for the purpose of preventing/reducing inflammatory damage caused by bacterial pneumonia." (PMID 38183438, 2024). "Because, NPY levels were higher in patients with bacterial pneumonia compared to healthy controls, while it was lower in patients with viral pneumonia." (PMID 38183438, 2024). "Our findings regarding increased NPY levels in bacterial pneumonia are consistent with this previous literature and imply a role of NPY in pathological processes in bacterial pneumonia." (PMID 38183438, 2024). "In the current study, besides elevated levels of CGRP, SP, VIP, NPY, and PCT peptides in bacterial pneumonia compared to controls, these were also all higher in bacterial pneumonia than in viral pneumonia." (PMID 38183438, 2024).
basophilic leukemia (1 paper, 2018). "The neuropeptide Y (NPY), which was reported to colocalize with serotonin in the secretory granules, fused to GLase (NPY-GLase) was efficiently expressed in rat basophilic leukemia (RBL-2H3) cells, a mast-cell line, using a preferred human codon-optimized gene." (PMID 30042943, 2018).
behavioral disorders (1 paper, 2019). "If mammalian NPY is inherited in epigenetically modified states, then this would require a fundamental change in how we study and view inheritance of NPY-related behavioral disorders and possible effects of parental environment." (PMID 31287057, 2019).
blastoma (1 paper, 2018). A malignant neoplasm composed of undifferentiated cells. "The present study showed that haloperidol decreased NPY expression in both human blastoma SH-SY5Y and primary striatal neurons." (PMID 30374288, 2018).
brain injury (1 paper, 2025). Acute and chronic (see also brain INJURIES, CHRONIC) injuries to the brain, including the cerebral hemispheres, CEREBELLUM, and brain STEM. "In the model of diffuse brain injury, the number of NPY + neurons decreased in the supragranular and infragranular layers of the cortex 24 h after injury, but returned to control values 14 days post-TBI." (PMID 40711610, 2025).
breast adenocarcinoma (1 paper, 2023). "The pre-pro NPY protein expression was upregulated in human breast adenocarcinomas, but the NPY protein level was downregulated." (PMID 37373115, 2023).
central nervous system infection (1 paper, 2021). "NPY as a negative regulator of monocyte recruitment into the central nervous system provides a potential therapeutic target for inhibiting central nervous system infection." (PMID 34422139, 2021).
central precocious puberty (1 paper, 2025). "In this study, it was aimed to compare the circulating levels of ghrelin, leptin, PYY and NPY between the girls with idiopathic central precocious puberty (ICPP) and prepubertal girls, and also to evaluate the alterations in the levels of these hormones during leuprolide acetate treatment." (PMID 38896175, 2025).
cerebral infarction (1 paper, 2012). An ischemic condition of the brain, producing a persistent focal neurological deficit in the area of distribution of the cerebral arteries. "In this study, we analyzed the distribution of NPY polymorphisms in dampness-phlegm pattern and non-dampness-phlegm pattern in elderly Korean subjects with cerebral infarction (CI)." (PMID 22110543, 2012).
cerebral small vessel disease (1 paper, 2022). Cerebral small vessel disease is the term currently used to pathological processes that affect the brain parenchymal circulation (arterioles, capillaries, and veins). "The IL-6, epinephrine, high-mobility group protein B1, neuropeptide Y, theta oscillations in the hippocampal neurons, and cerebral small vessel disease have been recently implicated in the pathogenesis of PSE." (PMID 36338344, 2022).
cholestasis (1 paper, 2018). Impairment of the bile flow caused by obstruction within the liver, or outside the liver in the bile duct system. "Cholangiocytes express NPY receptors as well as secrete and respond to NPY during cholestasis with increasing proliferation." (PMID 30109019, 2018).
Chronic constipation (1 paper, 2025). Constipation for longer than three months with fewer than 3 bowel movements per week, straining, lumpy or hard stools, and a sensation of anorectal obstruction or incomplete defecation. "Constipation as a symptom is mainly associated with changes in large intestine transit and previous studies have found that NPY immunoreactivity was increased in descending colon myenteric plexus of patients with idiopathic chronic constipation." (PMID 40142315, 2025).
chronic gastritis (1 paper, 2015). Inflammation of the stomach that is chronic in nature. "Furthermore, experiment in human depicted an increase in NPY- IR nerve endings within the mucosa during chronic gastritis caused by Helicobacter pylori." (PMID 26606050, 2015).
Co-infection (1 paper, 2020). "Co-infection with NPY-pHluorin and TeNT (4–5 days before imaging, identified by IRES-mCherry expression tag) disrupted DCV exocytosis (DCV fusion events control: 57 ± 19, TeNT: 0.14 ± 0.08) but did not alter the number or sub-cellular distribution of DCVs." (PMID 32616842, 2020).
colon adenocarcinoma (1 paper, 2023). "The data suggest that targeting the NPY/Y2R system is a promising antitumor strategy to treat colon adenocarcinomas." (PMID 37373115, 2023). "NPY and Y2R are overexpressed in human colon adenocarcinomas, orthotopic HT29, and VEGF-A-depleted orthotopic HT29 tumors." (PMID 37373115, 2023).
colorectal tumor (1 paper, 2021). "In the cohort, 23 primary colorectal tumor tissues were analyzed associated with 11 adjacent non-tumor tissues to measure DNA hypermethylation of NPY and WIF1, as potential new biomarkers of CRC in liquid biopsies." (PMID 34627187, 2021).
Constipation (1 paper, 2025). Infrequent or difficult evacuation of feces. "However, the results of the current study show that patients with constipation also have higher NPY gene expression in distal jejunal muscular tissue." (PMID 40142315, 2025).
coronary atherosclerosis (1 paper, 2023). Atherosclerosis of the coronary vasculature. "Together, elevated serum NPY levels seem to be associated with the occurrence of coronary atherosclerosis in Chinese adults." (PMID 38087221, 2023).
coronary stenosis (1 paper, 2019). Narrowing of the coronary artery lumen diameter. "Recently, more clinical studies identified that endogenous neuropeptide-Y could cause coronary artery constriction especially coronary microvascular spasm, in both patients without coronary stenosis and patients of ST-elevated myocardial infarction." (PMID 31637257, 2019).
COVID-19 (1 paper, 2024). A disease caused by infection with severe acute respiratory syndrome coronavirus 2. "Significantly higher ghrelin and NPY levels in the fasting condition were observed in the COVID-19 group than in the non-COVID-19 group (197.5 pg/mL vs. 67.1 pg/mL, p < 0.001 for ghrelin and 128.0 pg/mL vs. 84.5 pg/mL, p = 0.005)." (PMID 39064794, 2024). "While there is currently limited direct evidence of the influence of COVID-19 on NPY levels, the virus could potentially impact NPY through various mechanisms related to stress, inflammation, metabolism, and complications associated with infection." (PMID 39064794, 2024). "Significantly higher ghrelin and NPY levels were observed in the COVID-19 group than in the non-COVID-19 group (ghrelin 197.5 pg/mL vs. 67.1 pg/mL, p < 0.001; NPY 128.0 pg/mL vs. 84.5 pg/mL, p = 0.005)." (PMID 39064794, 2024).
delirium (1 paper, 2020). A disorder characterized by confusion; inattentiveness; disorientation; illusions; hallucinations; agitation; and in some instances autonomic nervous system overactivity. "The misregulation of the four HAR-Brain genes, namely APP, PLCB1, NPY, and HTR2A, in the M1 module is more likely to underlie delirium susceptibility rather than specifically be the molecular pathways driving the development of delirium." (PMID 33086708, 2020). "We found that four of the HAR-Brain genes, namely APP, PLCB1, NPY, and HTR2A, in the M1 module were highly connected and appeared to exhibit hub properties, which might play vital roles in delirium development." (PMID 33086708, 2020).
diarrhoea (1 paper, 2021). "Gathering the variety of pathophysiologic mechanisms resulting in diarrhoea and the important role of the ENS, we studied if OA-caused diarrhoea involves alteration of intestinal hormones (PYY) and/or neurotransmitters (5-HT and NPY)." (PMID 34148100, 2021). "It should be remarked the fact that all mice treated with the toxin or with the combination of both, OA and NPY (NPY-OA), developed diarrhoea." (PMID 34148100, 2021). "We performed a set of in vivo approaches to elucidate whether neuropeptide Y (NPY), Peptide YY (PYY) or serotonin (5-HT) was implicated in the early OA-induced diarrhoea." (PMID 34148100, 2021). "However, pre-treatment with NPY did not reduce OA-induced diarrhoea and intestinal fluid accumulation was only modestly improved." (PMID 34148100, 2021).
disc degeneration (1 paper, 2017). "In addition, recent studies of sensory neurons supplying intervertebral discs in small animal disc degeneration models demonstrated that the expression of NPY is increased, suggesting an enhanced nociceptive response and a contribution to discogenic pain." (PMID 28762133, 2017).
Dyskinesia (1 paper, 2014). A movement disorder which consists of effects including diminished voluntary movements and the presence of involuntary movements. "NPY has been proposed to exert neuroprotective effects on dopaminergic neurons, however further studies will be necessary to clarify its potential role in dyskinesia." (PMID 25254549, 2014).
Encephalopathy (1 paper, 2025). Encephalopathy is a term that means brain disease, damage, or malfunction. "Furthermore, increased neuropeptide Y (NPY)-like immunoreactivity has been observed in the cerebrospinal fluid of Patients with HIV, suggesting a potential link to HIV encephalopathy." (PMID 41303692, 2025).
endometrial cancer (1 paper, 2022). Primary or metastatic malignant neoplasm involving the endometrium (mucous membrane that lines the endometrial cavity). "Various neuropeptides, consisting of hypothalamic decapeptide GnRH, neuropeptide Y, and leptin were proven to have a tight association with endometrial cancer." (PMID 35893039, 2022).
folate deficiency (1 paper, 2019). A nutritional condition produced by a deficiency of FOLIC ACID in the diet. "Specifically, folate deficiency led to decreased NPY expression and to overexpression of AgRP mRNA, along with reduced expression of the leptin and insulin receptors, whereas ghrelin overexpression was associated with reduced expression of these receptors." (PMID 31615150, 2019).
gallstones (1 paper, 2017). Solid crystalline precipitates in the biliary tract, usually formed in the gallbladder, resulting in the condition of cholelithiasis. "Previous research reported that leptin-deficient or leptin-resistant obese mice exhibited decreased gallbladder responses to NPY and CCK compared with control mice with normal leptin metabolism, suggesting that leptin dysregulation is associated with gallbladder motility and gallstone formation." (PMID 29088261, 2017).
gastritis (1 paper, 2015). Inflammation of the stomach. "ASA- induced gastritis resulted in increased expression of NPY and GAL, as well as the novo-synthesis of nNOS and LENK in traced CCMG neurons." (PMID 26606050, 2015). "However, the exact function of NPY in neuronal response during ASA-induced gastritis in pigs remains unexplained and requires further investigation." (PMID 26606050, 2015). "Moreover, ASA- induced gastritis resulted in increased expression of NPY (76.59 ± 3.02%) and GAL (26.45 ± 2.75%) as well as the novo-synthesis of nNOS (6.13 ± 1.11%) and LENK (4.77 ± 0.42%) in traced CCMG neurons." (PMID 26606050, 2015). "ASA-induced gastritis led to the significant changes in the chemical coding of traced neurons, by reducing production of the catecholamine-synthesis tract enzymes and up-regulation of synthesis of neuropeptides involved in neuronal defence mechanisms (NPY, GAL, nNOS, LENK)." (PMID 26606050, 2015).
gingivitis (1 paper, 2024). A disorder involving inflammation of the gums; may affect surrounding and supporting structures of the teeth. "While periodontal therapy showed an improvement in salivary CgA, AA, β-endorphin, DHEA, and sIgA levels (p<0.05) in non-pregnant women with gingivitis; neuropeptide Y levels were found to be unaffected (p>0.05)." (PMID 38368525, 2024). "There were no significant changes in salivary CgA, AA, DHEA, sIgA, and neuropeptide Y levels in pregnant women with gingivitis (p>0.05); however, a decrease in β-endorphin levels was observed after therapy (p<0.05)." (PMID 38368525, 2024). "In the N-Pr gingivitis group, a statistically significant decrease was observed in salivary CgA, AA, β-endorphin, DHEA, and sIgA levels after periodontal therapy (p<0.05), with the exclusion of the NPY level which showed no alteration (p>0.05)." (PMID 38368525, 2024).
gonadotropin deficiencies (1 paper, 2026). "Increased NKB or NPY signaling may have elevated gonadotropin levels in animals with testes, as genetic knockouts of NKB receptors are associated with gonadotropin deficiencies in humans and mice, and NPY activates GnRH neurons." (PMID 41355063, 2026).
hand, foot and mouth disease (1 paper, 2023). A clinical syndrome that is usually caused by enterovirus infection, and that is characterized by fever, anorexia, and painful sores in the mouth, distal extremities, and/or other sites, including the buttocks. "Some researchers have proposed that curcumin can significantly elevate weight, reduce viral load and plasma D-dimer (D-D), the levels of neuron-specific enolase (NSE) and neuropeptide Y (NPY) in rats with severe hand-foot-and-mouth disease." (PMID 37719857, 2023).
hearing loss (1 paper, 2024). "Since NPY signaling dampens the excitability of most glutamatergic IC neurons, increased NPY expression following hearing loss might help keep enhanced central gain from driving hyperexcitability in the IC." (PMID 38585909, 2024).
hematoma (1 paper, 2021). A hematoma is a collection of blood from a vascular structure into an extravascular space. "This positive correlation also appeared between the serum NPY level and hematoma volume (r = 0.308, p = 0.206)." (PMID 34422139, 2021). "Linear correlation analysis showed that the serum NPY level of ICH patients was significantly positively correlated with the baseline NIHSS score (r = 0.413, p = 0.041) and hematoma volume (r = 0.308, p = 0.026)." (PMID 34422139, 2021). "Through further research, we also found that serum NPY concentration was positively correlated with the NIHSS score and hematoma volume." (PMID 34422139, 2021).
heroin addiction (1 paper, 2023). "In heroin addiction, the lower neuropeptide Y levels in iHUD at acute withdrawal (3 days) approach the level of HC after a month of abstinence." (PMID 37034753, 2023).